S1PR2 (sphingosine-1-phosphate receptor 2)
Diseases named in the same sentence as S1PR2 in open-access papers (continued):
Sharing a sentence is not in itself a finding about the gene and the disease.
colitis (11 papers, 2017 to 2026). Inflammation of the colon. "Research indicates that S1PR2-/-deficient mice exhibit heightened sensitivity to dextran sulfate-induced colitis, characterized by increased intestinal permeability and CD4+ T cell proliferation." (PMID 40599770, 2025). "JTE-013, an S1PR2 antagonist, partially protected against colitis-like pathology in the DSS-induced colitis model, and it’s derivatives have been shown to enhance the effects of 5-FU in resistant CRC cell lines." (PMID 38398179, 2024). "This was further supported with an increase in the mRNA expression of MHC-II in IECs from S1PR2 KO colitis mice compared to WT colitis mice suggesting that S1PR2 limits MHC-II expression and presentation to CD4+ T-cells." (PMID 36569849, 2022). "Administration of S1PR2 and ROCK1 antagonists was found to reduce the expression of CD86 and MCP-1 in an acute DSS model of colitis, suggesting that S1PR2 promotes polarization of macrophages to an M1/pro-inflammatory phenotype." (PMID 36569849, 2022). "DCA enema significantly aggravated DSS-induced colitis in mice and S1PR2 inhibitor as well as inflammasome inhibition by cathepsin B antagonist substantially reducing the mature IL-1β production and alleviated colonic inflammation superimposed by DCA." (PMID 29854830, 2018). "DCA enema strongly aggravates DSS-induced colitis in mice and S1PR2 antagonist as well as inhibition of cathepsin B substantially alleviate colonic inflammation imposed by DCA." (PMID 29854830, 2018). "Here, we sought to explore the detailed molecular mechanism involved and examine the effect of S1PR2 blockage in a colitis mouse model." (PMID 29854830, 2018). "We sought to study whether blockage of S1PR2 could prevent the proinflammatory role of DCA instillation in DSS-induced colitis; thus, S1PR2 antagonist JTE-013 was intraperitoneally administrated." (PMID 29854830, 2018). "Enhanced expression of S1PR2 observed in colitis may therefore result in enhanced activation of downstream signaling pathways and exacerbated response to S1P." (PMID 28493876, 2017). "S1PR2 activation has been reported to strengthen tight junctions via PI3K/AKT in epithelial cells, while in inflammatory contexts, S1PR2 expression increases and its inhibition reduces permeability and injury in DSS colitis models." (PMID 41481156, 2026). "Both colitis-induced and genetic Apc+/min mouse models of CRC showed a higher incidence in size and number of carcinomas and/or high-grade adenomas, with increased cell proliferation in S1PR2−/− mice compared to S1PR2+/+ controls." (PMID 33225975, 2020).
Cerebral ischemia (10 papers, 2018 to 2023). Restriction of arterial blood supply to the brain associated with insufficient oxygenation to support the metabolic requirements of the tissue. "In conclusion, miR-149-5p had a regulatory effect on S1PR2 of pericytes after acute cerebral ischemia reperfusion in rats and had a neuroprotective effect by regulating the expression levels of MMP9 and SODs." (PMID 34224319, 2021). "Another independent study also suggested that S1PR2 was involved in neuroinflammatory after tMCAO, and S1PR2 may mainly participate in the pro-inflammatory response of activated microglia during cerebral ischemia." (PMID 35242008, 2022). "In this study, a rat model of acute cerebral ischemia reperfusion was established, and miR-149-5p was infected with pericytes in the test model group, so as to detect the regulatory and neuroprotective effects of miR-149-5p on the expression level of S1PR2 in pericytes." (PMID 34224319, 2021).
glioblastoma (10 papers, 2016 to 2024). The most malignant astrocytic tumor (WHO grade IV). "As a result, SPARC prevents Nogo-A from further activating S1PR2 and thus enables glioblastoma cells to invade white matter." (PMID 31062076, 2019). "Interestingly, S1PR1 and S1PR2 pointed out high expression levels in patients with glioblastoma multiforme (GBM)." (PMID 38419070, 2024). "Glioblastoma cells seem to exploit the structural flexibility of Nogo-A-Δ20 using SPARC as a soluble decoy to attenuate the activation of inhibitory RhoA signaling via S1PR2." (PMID 31062076, 2019). "The expression of S1PR2 by glioblastoma cells may be explained by their requirement to balance the input from other expressed S1P receptor subtypes, such as S1PR1 or S1PR3." (PMID 31062076, 2019). "Similarly, Nogo-A-Δ20 activated S1PR2 in glioblastoma cells, and this activation could be attenuated by the receptor antagonist JTE-013." (PMID 31062076, 2019). "In glioblastoma multiforme (GBM), one of the brain tumors with worse prognosis, increased expression of S1PR1 and S1PR2 correlated with decreased patient’s survival." (PMID 27800303, 2016). "Reduced IRE1α activity enables glioblastoma cells with activated AKT signaling to secrete SPARC, which prevents an intrinsically disordered region of Nogo-A-Δ20 from further inducing RhoA signaling via S1PR2." (PMID 31062076, 2019). "NIH-3T3 fibroblasts, which do not express NgR1, activated S1PR2 in the presence of Nogo-A-Δ20, similar to glioblastoma cells [Suppl." (PMID 31062076, 2019). "Moreover, SPARC production occurred only when Nogo-A activated S1PR2 in trans, whereas overexpression of Nogo-A in glioblastoma cells did not induce SPARC [Suppl." (PMID 31062076, 2019). "S1PR2 has an ability to enhance the expression of plasminogen activator inhibitor-1 (PAI-1) and urokinase-type plasminogen activator receptor (uPAR) through the activation of dual downstream signaling cascades MEK1/2 and Rho-kinase, which are vital for glioblastoma invasiveness." (PMID 29149079, 2017).
colon carcinoma (9 papers, 2015 to 2025). "Findings from this study suggest that oxaliplatin resistance in colon cancer cells involves the activation of SphK1/S1P/S1PR2 signaling axis that activates ERK signaling pathway resulting in the induction of CD44 expression." (PMID 32456134, 2020). "Further studies are warranted to ascertain the role of S1PR2 in regulating the behavior of colon cancer cells and determine its therapeutic significance." (PMID 32456134, 2020). "To address the role of S1PR2 during the early phases of tumor development, we inhibited pharmacologically S1PR2 in ApcMin/+ mice at 10 weeks of age, before the appearance of both intestinal and colonic tumors, by the specific S1PR2 inhibitor (JTE013)." (PMID 33225975, 2020). "To this end, we firstly examined the endogenous expression of S1PR2 in four metastatic colon cancer cells SW620, RKO, HCT116, and HT29." (PMID 33225975, 2020). "Indeed, the loss of S1PR2 induces the expansion of intestinal stem cells in colon cancer cells and, clinically, S1PR2 expression was lost in 33% of adenocarcinomas with stage II/III pT3-T4 and significantly decreased in 55%." (PMID 35889921, 2022). "Given that the expression of S1PR2 was elevated in benign adenomas but markedly declined in carcinoma, these authors hypothesized that S1PR2 may have a tumor suppressor role in colon cancer." (PMID 32456134, 2020).
diffuse large B-cell lymphoma (9 papers, 2015 to 2024). "S1PR2 mutational inactivation or deletion confers proliferative advantage in diffuse large B-cell lymphoma (DLBCL) cell lines in vitro and in vivo mouse models." (PMID 35565311, 2022). "This is based on findings that around 25% of human germinal center-derived diffuse large B cell lymphomas show somatic mutations in the S1PR2 gene, and S1PR2-deficient mice develop B cell lymphomas at an advanced age." (PMID 35163211, 2022). "The importance of S1PR2 in lymphoma is underlined by the fact that the gene is mutated in approximately 25% of cases of diffuse large B cell lymphoma (DLBCL)." (PMID 25938000, 2015). "Interestingly, high SMAD1 level could activate S1PR2 expression and induce apoptosis in diffuse large B-cell lymphoma." (PMID 34134766, 2021). "In diffuse large B-cell lymphoma (DLBCL) cell lines, expression of S1PR2 reduces tumor growth and is a good prognosis factor for patient survival." (PMID 27800303, 2016).
Insulin resistance (9 papers, 2016 to 2025). Increased resistance towards insulin, that is, diminished effectiveness of insulin in reducing blood glucose levels. "Studies have reported that S1P in the extracellular environment binds to S1PR2 on hepatocytes, which results in diminished insulin signaling and insulin resistance (IR)." (PMID 34950103, 2021). "Additionally, bile acid-activated S1PR2 displays insulin-like activity in hepatic glucose regulation, whereas S1PR2 antagonists prevent palmitic acid-mediated insulin resistance." (PMID 39935473, 2025). "Furthermore, these substances can induce insulin resistance by interacting with receptors such as S1PR2, thereby contributing to systemic metabolic disturbances, including metabolic syndrome." (PMID 40807240, 2025). "In this regard, it needs to be noted that S1P signaling through S1PR2 has been shown to interact with insulin signaling, and might participate in the development of insulin resistance in peripheral cells." (PMID 37794263, 2024). "Therefore, it is likely that the increase in insulin resistance and glucose intolerance observed in S1PR3−/− mice maybe due to a combined dual effect of the loss of S1PR3 signalling and increased expression of S1PR2." (PMID 35094654, 2022). "Thus, S1PR2 might contribute to the development of central insulin resistance." (PMID 37794263, 2024). "Upon binding to its bile acid-derived ligands, S1PR2 potentiates the PI3K/Akt insulin-signaling axis, thereby enhancing peripheral glucose uptake and improving insulin sensitivity, indicating that this receptor–ligand axis constitutes a promising therapeutic target for insulin resistance." (PMID 40807240, 2025).
Stroke (9 papers, 2015 to 2023). Sudden impairment of blood flow to a part of the brain due to occlusion or rupture of an artery to the brain. "Previous in vivo studies showed that pharmacological inhibition of S1pr2 blocked the development of spontaneous hemorrhagic transformation and protected cerebrovascular integrity in an experimental stroke animal model." (PMID 35836816, 2022). "Studies also pointed out that the expression of miR-149-5p in the cells of stroke model rats was significantly reduced, which was negatively correlated with the expression of S1PR2." (PMID 34224319, 2021). "S1PR2 gene can block the occurrence and development of cerebral edema and other complications after stroke through the regulation of matrix metalloproteinase (MMP-9)." (PMID 34224319, 2021). "Altogether our in vitro and in vivo data in mice and humans point to S1PR2 as an attractive therapeutic target for cerebrovascular protection in stroke and other instances of hypoxic or inflammatory injury in cerebral blood vessels." (PMID 26243335, 2015). "In this study, we found that S1PR2 inhibition potently blocked the development of spontaneous haemorrhagic transformation in experimental stroke, which was observed after a more severe ischaemic injury." (PMID 26243335, 2015). "To determine the therapeutic time window of JTE013 in experimental stroke, we assessed the oedema and infarct ratios after delayed administration of the S1PR2 antagonist." (PMID 26243335, 2015). "Altogether our data point to S1PR2 as a novel therapeutic target for acute cerebrovascular protection in stroke." (PMID 26243335, 2015). "Inhibition of S1PR2 potently blocked the development of cerebral oedema and spontaneous haemorrhagic transformation in experimental stroke." (PMID 26243335, 2015). "To evaluate the therapeutic targeting of S1PR2 in stroke reperfusion therapies, we acutely inhibited S1PR2 activation by administration of the S1PR2 antagonist, JTE013 by gavage." (PMID 26243335, 2015). "Here, by using genetic and pharmacological approaches, the authors show that S1PR2-mediated signaling is crucial for the disruption of cerebrovascular integrity and development of intracerebral haemorrhage in a mouse stroke model." (PMID 26243335, 2015). "Interestingly, active forms of MMP have been associated with the development of vasogenic edema and disruption of blood vessel integrity in stroke reperfusion therapy and S1PR2 has recently been shown to be critical in MMP-9 activation." (PMID 26884643, 2016). "In our study, we found that S1PR2 expression is detected in brain microvessels after stroke, which together with our in vitro data with brain endothelial cells, neurons and glial cells, indicate that S1PR2 plays a critical role in the disruption of cerebrovascular integrity." (PMID 26243335, 2015). "By using genetic approaches and a S1PR2 antagonist (JTE013), here we show that S1PR2 plays a critical role in the induction of cerebrovascular permeability, development of intracerebral haemorrhage and neurovascular injury in experimental stroke." (PMID 26243335, 2015). "Altogether these data indicate that S1PR2 plays a critical role in MMP-9 activation and the induction of gelatinase activity in cerebral microvessels after I/R injury in experimental stroke." (PMID 26243335, 2015). "We also found that the S1PR2 antagonist, JTE013, is protective when given within 4.5 h of stroke onset (therapeutic time window)." (PMID 26243335, 2015). "For example, S1PR2 expression has been reported in brain endothelial cells and its activity increased MMP-9 activity and promoted blood-brain barrier permeability during stroke." (PMID 28725183, 2017). "To study the role of S1PR2 signalling in the regulation of neurovascular responses to I/R injury, we used a mouse model of transient focal cerebral ischaemia, the transient MCAO (tMCAO) mouse model of stroke." (PMID 26243335, 2015).
asthma (8 papers, 2014 to 2025). "Beyond established roles in ARDS, IPF, and asthma, S1PR2 has also been implicated in the pathogenesis of other pulmonary diseases, including lung cancer, and COPD." (PMID 41511294, 2025). "These functional changes are supported by S1PR2-driven calcium mobilization, a key trigger for smooth muscle contraction, and contribute to airway hyperresponsiveness, a defining feature of asthma pathophysiology." (PMID 41511294, 2025). "Beyond immune regulation, S1PR2 signaling further contributes to the pathophysiology of asthma by promoting airway hyperresponsiveness, intracellular calcium sensitization, and airway smooth muscle cell proliferation." (PMID 41511294, 2025). "In murine models of ovalbumin (OVA)-induced asthma, pharmacological inhibition of S1PR2 with JTE-013 significantly reduced levels of key inflammatory cytokines, including IL-1, IL-4, IL-5, as well as serum IgE levels in BALF." (PMID 41511294, 2025). "Further studies investigating the effects of the S1PR2 antagonist at different intratracheal dosage levels on asthma would be of great interest." (PMID 27829417, 2016). "To investigate the effects of the S1P/S1PR2 axis on bronchial asthma, we employed an experimental asthma mouse model and evaluated the therapeutic effects of JTE013." (PMID 27829417, 2016). "Future translational work in vivo using S1PR2 antagonists in animal models of asthma will be of great interest." (PMID 24743449, 2014). "This study reveals S1PR2 and NF-κB as potential therapeutic targets in neutrophilic airway diseases such as severe asthma." (PMID 24743449, 2014). "Emerging data also implicates S1PR2 in the regulation of autophagy during asthma progression." (PMID 41511294, 2025). "Alterations in the expression levels of S1PR isoforms have been demonstrated in other pathological states for instance upregulation of S1PR1 and S1PR3 and downregulation of S1PR2 were reported in multiple sclerosis lesions and in experimental asthma, respectively." (PMID 28493876, 2017). "Therefore, our results showed that, the serum IgE expression level was enhanced in the asthmatic mice, which could be inhibited by the JTE-013 treatment, indicating that S1P inhibited the mast cell activity and reduced the inflammation in asthma through S1PR2." (PMID 33643037, 2020). "This work highlights that S1PR2 signaling regulates fundamental physiological and pathological processes, including maintaining endothelial and epithelial barrier integrity in ARDS, promoting fibrotic remodeling in IPF, and driving airway inflammation and hyperresponsiveness in asthma and COPD." (PMID 41511294, 2025). "This literature provides evidence that S1PR2/Rho kinase signaling could drive asthma pathogenesis not only by augmenting neutrophilic inflammation, but also by increasing airway smooth muscle contractility." (PMID 24743449, 2014).
liver disease (8 papers, 2016 to 2025). "Reducing S1PR2 activation may be also useful for improving cognitive function in patients with liver disease and hepatic encephalopathy and, likely, in other pathologies associated with neuroinflammation." (PMID 38139078, 2023). "Conjugated bile acids activate S1PR2 to regulate inflammation in some liver diseases." (PMID 34943862, 2021). "S1P/S1PR2/3 plays a crucial role in regulating M1 type polarization of BMMs and acts by activating the G(α)i/o/PI3K/JNK signaling pathway, with potential implications for new approaches to inflammatory liver disease therapy." (PMID 34943862, 2021).
lymphoma (8 papers, 2012 to 2025). A malignant (clonal) proliferation of B- lymphocytes or T- lymphocytes which involves the lymph nodes, bone marrow and/or extranodal sites. "Consistently, low S1PR2 expression is associated with worse prognosis, compared to high S1PR2 expression in patients with lymphomas—making S1PR2 a positive prognostic marker for patients with DLBCL." (PMID 35565311, 2022). "In addition, even if the mechanisms of S1PR2 lymphoma suppressor function remain to be elucidated, S1PR2-deficient mice develop tumors displaying histologic and molecular features of GC-derived DLBCL and S1PR2 is aberrantly mutated in 26% of human DLBCL." (PMID 22973275, 2012). "In fact, patient samples of lymphomas from secondary lymphoid organs (SLOs) had higher expression of S1PR2, while samples from ocular adnexal lymphomas (OAL) had higher S1PR3 expression." (PMID 36361536, 2022). "Similarly, S1pr2−/− mice develop B-cell lymphoma, thus supporting that disruption of S1PR2 seems to have lymphoma-promoting effects." (PMID 36361536, 2022). "Additionally, ectopic S1PR2 expression decreases lymphoma tumor sizes in vivo." (PMID 35565311, 2022). "Furthermore, about 50% of mice with targeted disruption of S1PR2 develop lymphoma." (PMID 25938000, 2015).
melanoma (8 papers, 2015 to 2023). A malignant, usually aggressive tumor composed of atypical, neoplastic melanocytes. "As far as S1PR2 is concerned, S1PR2 signaling induces acute myeloid leukemia growth or proliferation and mediates tumor metastasis in bladder cancer and melanoma cells." (PMID 31807117, 2019). "Moreover, the genetic deletion of S1PR2 promoted the growth of melanoma and Lewis lung carcinomas in vivo, supporting S1PR2 as a critical regulator of cell proliferation." (PMID 33225975, 2020). "Indeed, S1PR2 negatively regulates migration and invasion of human melanoma, glioblastoma, oral squamous cell carcinoma, and gastric cell lines and cell proliferation in human renal tumor cells." (PMID 33225975, 2020). "Indeed, stimulation or inhibition of S1P-induced migration in melanoma cells depends on expression of S1PR1 or S1PR2, respectively." (PMID 27800303, 2016). "Moreover, we have recently demonstrated that activation of NF-κB by extracellular S1P in melanoma cells involved both S1PR1 and S1PR2 and was inversely correlated with the expression of the actin-binding protein FlnA." (PMID 27800303, 2016).